EPO (erythropoietin)
Diseases named in the same sentence as EPO in open-access papers (continued):
Sharing a sentence is not in itself a finding about the gene and the disease.
anemia (continued). "Anemia in individuals with diabetes-related kidney disease is frequently associated with a reduction in the production of erythropoietin by the kidneys." (PMID 37868469, 2023). "It is typical for anemia to be present at various stages of cancer because of blood loss, reduced erythropoietin production or diminished erythropoietin efficiency, and depletion of critical nutrients." (PMID 36982153, 2023). "In fact, under these conditions, treatment with BMOV reduced hepcidin levels, increased intracellular erythropoietin signaling, and restored non-iron deficiency anemia." (PMID 37298322, 2023). "For instance, the protective or aggravating effects of different hormones (EPO, hepcidin, etc.), inflammation, acidosis, and anemia or other causes of hypoxia should be investigated." (PMID 37108056, 2023). "ESAs, such as recombinant human EPO (epoetin alfa or rHuEPO) and its hyperglycosylated derivative darbepoetin alfa, are standard-of-care therapies for the treatment of anemia associated with CKD." (PMID 38125882, 2023). "Anemia is primarily linked to LN due to impaired erythropoietin production induced by inhibiting inflammatory cytokines and serum b2MG." (PMID 36205758, 2023). "We then performed a head-to-head comparison of optimized circRNA versus CleanCap and 100% N1Ψ-modified mRNA in vivo using RNAs encoding human erythropoietin (hEPO), a secreted protein used to treat anemia." (PMID 35851375, 2023). "Extensive burns cause anemia and critical illness, and the only therapeutic alternative is blood transfusion since erythropoietin and iron supplements fail to promote effective erythropoiesis." (PMID 36700031, 2022). "Anemia occupied the highest proportion of perioperative complications in our study, which is related to the reduction in erythropoietin and myelosuppression caused by the long-term accumulation of metabolic waste." (PMID 35933366, 2022). "Tumor cells produce pro-inflammatory cytokines (e.g., TNF-α, IL-1, IL-6) that cause anemia, reduce erythrocyte lifespan, and alter energy metabolism by altering iron homeostasis, inhibiting erythropoiesis and blocking EPO synthesis, and affecting EPO activity." (PMID 36567722, 2022). "Jujube polysaccharides have been showed the improvement on chronic kidney disease-associated anemia by alternating the serum EPO level, kidney EPO mRNA and protein expression." (PMID 35250989, 2022). "In 1989, rhEPO was approved by the Food and Drug Administration of the United States of America for clinical treatment of anemia associated with chronic renal failure due to insufficient EPO production and showed improvement in the life quality of patients." (PMID 35250554, 2022). "These last observations were consistent across different causes of anemia, and the hemoglobin threshold at which the association between inflammation and erythropoietin reversed was approximately hemoglobin 13.0 g/100 mL." (PMID 35160156, 2022). "Suboptimal production of erythropoietin in the kidney is one of the common causes of anemia in aging, in addition to bone marrow failure." (PMID 35740448, 2022). "First, anaemia occurs as a complication of chronic kidney disease, caused by inadequate production of erythropoietin, associated with increased morbidity and mortality." (PMID 36547277, 2022). "Because of the deficiency of renal erythropoietin production, the production of red blood cells in the bone marrow decreases, resulting in anemia and gradual development of physical symptoms due to uremia." (PMID 36227926, 2022). "In particular, diminution of renal function leading to depressed erythropoietin production is a major cause of anemia." (PMID 35490226, 2022). "The primary cause of anemia in chronic kidney disease patients represents a decrease in EPO synthesis." (PMID 35464768, 2022). "A decrease in endogenous EPO production causes anemia that can be treated with recombinant Human EPO (rHuEPO)." (PMID 35292912, 2022).
anemia (continued). "For patients with pSS, erythropoietin or ferralia should be given preoperatively to optimize hemoglobin levels, thus reducing the risk of postoperative anemia and even blood transfusion." (PMID 36556054, 2022). "MIS is directly linked with erythropoietin hyporesponsiveness in hemodialyzed individuals and makes treatment of anemia, the most common complication of end-stage renal disease (ESRD), very challenging." (PMID 36558477, 2022). "The pathogenesis of anemia is very complex: the main role is played by a relative deficit of EPO; iron deficiency is the second main contributor." (PMID 36142976, 2022). "This was confirmed and extended in a mouse model of EPO-deficient anemia to show that during Fe overload renal interstitial fibroblasts accumulate Fe, and this impairs the hypoxia-driven transcription of the Epo gene via renal HIF2." (PMID 35445830, 2022). "Evaluation for causes of his hypoproductive anemia (nutritional deficiencies, hemoglobinopathies, and hormonal imbalances) was unremarkable, and his anemia worsened despite increasing erythropoietin and darbopoetin doses." (PMID 34655156, 2022). "The results indicated that chronic Cd-intoxication causes anemia by disturbing the EPO production capacity of renal cells." (PMID 35445830, 2022). "In NTDT mice, apotransferrin infusion improved anemia, splenomegaly and plasma EPO, decreased membrane-associated α- globin precipitates and normalized the RBC half-life." (PMID 36079046, 2022). "We further demonstrated that anemia was associated with iFGF23, independently of renal function, EPO, and age." (PMID 35739404, 2022). "Hepcidin is upregulated by iron levels, inflammation and infection, while anemia, hypoxia, iron deficiency, ineffective erythropoiesis and increased erythropoietin (EPO) levels are down-regulating factors." (PMID 36079046, 2022). "There are numerous causes that contribute to anemia: hypersplenism, hemolysis, renal disfunction with consecutive reduced erythropoietin production, nutritional deficiency, systemic inflammation, bone marrow damage, and treatment related toxicity." (PMID 35626439, 2022). "The treatment of CKD-associated anemia was revolutionized by the introduction of EPO and ESAs, but safety concerns of ESA use have lately been emerged." (PMID 35222025, 2022). "The reasons for anemia were previously thought to be deficient erythropoietin production and poor iron uptake in CKD patients, but therapies intended to increase erythropoietin and iron levels were only effective in a minority of patients." (PMID 35432360, 2022). "The combination of routine laboratory biomarkers with specific analyses, including hepcidin, EPO and sTfR, can help physicians elucidate the pathophysiology, diagnose, and treat children with anemia caused by different etiologies." (PMID 35177695, 2022). "Anemia onset in chronic kidney disease patients is primarily caused by reduced erythropoietin levels and disrupted iron metabolism." (PMID 35156909, 2022). "Anaemia resulting from CKD in type 2 diabetes is due to impaired production of erythropoietin by peritubular fibroblasts, nutritional deficiencies (iron, folate, and B12), inadequate response to erythropoietin, and background proinflammatory conditions." (PMID 36340870, 2022). "Currently, EPO can be considered in the treatment of anemia associated with chemotherapy and chronic kidney disease." (PMID 36211426, 2022). "The reduction of erythropoietin (EPO) production by renal tubular fibroblasts is the primary cause of CKD-related anemia." (PMID 36324690, 2022). "Its increase has also been related to a decrease in the risk of developing anemia but, eventually, with a higher erythropoietin dose requirement in case of anemia." (PMID 36289903, 2022). "The etiology of CKD-associated anemia is complex with the contribution of reduced production of erythropoietin (EPO), a kidney-derived factor responsible for stimulating erythropoiesis, shortened red blood cell lifespan, and iron deficiency." (PMID 35222025, 2022).
anemia (continued). "RXRα deficient mice exhibit a transient anemia (E9.5–E11.5 in mouse) due to the inability to induce erythropoietin (Epo) gene expression, but they look normal at E12.5." (PMID 35269942, 2022). "Although a relative deficiency of EPO production is the main cause of anemia in CKD, iron metabolism is closely regulated at various stages of the red blood cell (RBC) life cycle." (PMID 36324690, 2022). "In patients with chronic kidney disease (CKD), including those undergoing HD, erythropoietin (EPO)-producing cells are dysfunctional, and anemia is caused by a decrease in the production of endogenous EPO." (PMID 36140193, 2022). "Recent findings have found reduced EPO, and anemia are independent risk factors for microvascular diseases including DKD." (PMID 36246564, 2022). "The limited treatment options for PMF-associated anemia include androgens, recombinant erythropoietin, prednisone and thalidomide, but they offer low response rates and short duration of response." (PMID 36278584, 2022). "In this context anaemia is a multifactorial process due to relative erythropoietin (EPO) deficiency, uremic-induced inhibitors of erythropoiesis, shortened erythrocyte survival, and disordered iron homeostasis." (PMID 36266621, 2022). "Myelosuppression by radiation, chemotherapy, and erythropoietin (EPO) stimulant agents for anemia can cause FID." (PMID 36567722, 2022). "The appearance of pale oral mucosa in ESRD patients explained mainly by anemia caused by erythropoietin and folic acid deficiencies." (PMID 34306534, 2021). "Increased levels of EPO in blood or amniotic fluid have also been reported in neonates with severe anemia caused by hemolytic anemia and Rh immunization." (PMID 33995348, 2021). "Given that hepcidin is cleared by the kidney, its serum levels are increased in renal failure patients with anemia and associated with iron-restricted erythropoiesis and resistance to recombinant human erythropoietin treatment." (PMID 34222290, 2021). "The kidney disease anemia, caused by the deficiency of a hormone, erythropoietin, is also treated with the replacement of recombinant human erythropoietin, which is also offered by the SUS." (PMID 33570082, 2021). "In patients with CKD, there is an absolute or a relative deficiency of erythropoietin production, which results in the development of anemia." (PMID 34136787, 2021). "Anemia is one of the most common complications of chronic kidney disease (CKD), with iron-deficiency anemia being the most common manifestation besides a decrease in erythropoietin activity." (PMID 34886434, 2021). "In many cases of CIA however, substantial hemolysis, evident from haptoglobin consumption, contributes to anemia as do other contributing factors such as EPO and vitamin deficiencies." (PMID 33842333, 2021). "The treatment of CKD-associated anemia is with erythropoiesis-stimulating agents (ESAs)—recombinant human erythropoietin (rHuEPO) such as epoetin alpha and epoetin beta—and iron supplementation." (PMID 33918412, 2021). "The possible mechanisms of hypertensinogenic effect of erythropoietin have been studied in animals as well as humans: both normal subjects, patients with anemia due to other causes and CKD patients." (PMID 33628672, 2021). "Erythropoiesis-stimulating agents (ESAs), including recombinant erythropoietin (EPO) analogs, have been used for treating anemia associated with CKD through compensating for decreased EPO." (PMID 33923349, 2021). "The primary cause of anemia in CKD is the reduced production of erythropoietin (EPO), however, approximately 5–43% of patients exhibit hyporesponsiveness to erythropoiesis-stimulating agents (ESAs) despite adequate dosing." (PMID 34222290, 2021). "High flux hemodialysis and online hemodiafiltration allow better clearance of middle molecules implicated in inflammation, and erythropoietin refractory anemia." (PMID 34718902, 2021).
anemia (continued). "Patients with CKD characteristically display a high level of anaemia that is mainly associated with impaired erythropoietin production, although haemolysis and a significantly shortened erythrocyte survival time have also been implicated." (PMID 33578719, 2021). "They suggested that eryptosis can cause chronic haemolysis and anaemia and that reasonable treatment can be provided using erythropoietin." (PMID 34174794, 2021). "Cd-induced anemia is caused by decreased erythropoietin production, iron deficiency and hemolysis due to RBC deformity." (PMID 35010453, 2021). "Most EPO-related research in SLE has focused on the association between anemia and autoantibodies to EPO and EPOR." (PMID 33796104, 2021). "Current FDA-approved indications for EPO include treatment of anemia associated with chronic kidney disease (CKD) or chemotherapy." (PMID 33796104, 2021). "On the other hand, androgen deficiency is also correlated with increased incidence of anemia, and the addition of androgens to EPO therapy seemed to increase the responsiveness of erythroid progenitors to EPO." (PMID 33918412, 2021). "In 1989, recombinant human erythropoietin (EPO) was approved for use in dialysis‐associated anemia, yet 3 years later only 60% of patients on dialysis were being treated to target hemoglobin (Hb) concentrations and many not at all." (PMID 33580972, 2021). "Anemia associated with kidney disease is considered to result in large part from insufficient production of renal erythropoietin (EPO) and subsequent decrease of erythropoiesis." (PMID 34657570, 2021). "The primary cause of anaemia in patients with end-stage renal disease is inadequate erythropoiesis caused among others by insufficient production of erythropoietin." (PMID 34895154, 2021). "Preoperatively, consideration should be given to the correction of underlying coagulopathy and anaemia, by the use of iron replacement or erythropoietin." (PMID 34298814, 2021). "Anemia in patients with CKD is the result of a deficient synthesis of erythropoietin, generating an imbalance between the oxygen demand and supply in the cells." (PMID 34441451, 2021). "In iron-deficiency anemia, erythropoietin—secreted to increase the number of red blood cells—secretion increases to stimulate platelet formation, inducing thrombocytosis to create a thrombus." (PMID 34207841, 2021). "Typically, carnitine deficiency is associated with various symptoms such as erythropoietin-resistant anemia, muscle weakness, cardiac dysfunction, and intradialytic hypotension." (PMID 34805230, 2021). "As massive urinary losses of EPO are expected in CNS, a trial of EPO therapy should be considered in patients with anaemia after correction of iron deficiency." (PMID 33514942, 2021). "The main mechanism of anemia in CKD has been historically recognized in erythropoietin (EPO) deficiency, which is responsible for poor maturation and differentiation of RBC precursors." (PMID 34209294, 2021). "Patients with CKD have high levels of anemia, which is mainly associated with impaired erythropoietin production, increased hemolysis and significantly shortened erythrocyte survival." (PMID 34200667, 2021). "The ERI is an indicator for the severity of erythropoietin-resistant anemia, and it is associated with the mortality rate in patients undergoing dialysis." (PMID 34805230, 2021). "The main cause of anemia in CKD patients is represented by the reduction in erythropoietin (EPO) production." (PMID 34356993, 2021). "Following the cloning of the human EPO gene, recombinant human EPO was approved for clinical use by the United States Food and Drug Administration in 1989 primarily for treatment of anemia associated with chronic renal disease." (PMID 34603036, 2021).
anemia (continued). "The multitude of factors implicated in anemia in critical illness includes decreased production of erythropoietin (EPO), inadequate EPO-induced bone marrow response, and diminished red cell survival, as well as treatment-associated traumatic blood loss." (PMID 34777198, 2021). "Women with intragestational serum ferritin levels <12 μg/L and women with intragestational erythropoietin >75th percentile had a two-fold and three-fold higher risk, respectively, of anemia at delivery." (PMID 33513722, 2021). "A case study was published reporting on two Thoroughbreds that developed anti-rHuEPO antibodies which ended up cross-reacting with endogenous EPO, decreasing erythropoiesis and causing anemia." (PMID 34946824, 2021). "The etiology of anemia in heart failure is multifactorial, with absolute and functional iron deficiency, decreased erythropoietin levels and erythropoietin resistance, inflammatory state and heart failure medications being the important causative factors." (PMID 34453627, 2021). "Among patients with advanced chronic kidney disease (CKD), anemia is due to multiple mechanisms: decreased EPO production, iron deficiency, blood loss, inflammation, and decreased survival of erythrocytes." (PMID 33467674, 2021). "Heart failure can lead to anemia through various mechanisms, such as iron deficiency, inflammation, low erythropoietin levels, medications, hemodilution, and medullar dysfunction." (PMID 34575335, 2021). "All these iron carriers can be heavily upregulated, as DMT1, up to 4–12-fold during iron deficiency anemia and erythropoietin increase." (PMID 33263170, 2021). "The suppression of erythrocyte maturation by inflammatory cytokines causes anisocytosis and abnormal erythropoietin function, which is associated with anemia, thrombotic state, and hemorrhagic tendency." (PMID 34063772, 2021). "One of the main causes of anaemia in patients with end-stage renal disease is relative deficiency in erythropoietin production." (PMID 34895154, 2021). "Instead, inappropriately low EPO levels were associated with the most severe fetal anemia in this population." (PMID 33995348, 2021). "Low erythropoietin levels are a major cause of early anemia in patients with impaired glucose homeostasis." (PMID 34789178, 2021). "Although the main cause of anemia in CKD is the relative deficit of renal production of erythropoietin (EPO), iron deficiency plays a crucial role in its genesis." (PMID 32087684, 2020). "CKD leads to a disruption of this process, erythropoietin deficiency and subsequent anemia, characterized by lower than normal number of circulating red blood cells or decreased levels of hemoglobin (Hgb)." (PMID 31587136, 2020). "The causes of anaemia in end-stage renal disease include a relative deficiency in erythropoietin production and complex clinical conditions such as iron deficiency, inflammation, and haemolysis." (PMID 32993543, 2020). "The treatment of anemia with erythropoietin (EPO) was associated with great benefits for some patients but not all." (PMID 31979104, 2020). "Recombinant human erythropoietin (rHuEPO) is a biotechnologically derived drug widely used in the treatment of different types of anemia, like anemia associated with chronic kidney disease, in HIV-infected or cancer patients." (PMID 32748255, 2020). "Here also, the shortened red cell survival and lowered erythropoietin response that is associated with SCA have a bearing towards the development of anaemia in SCA." (PMID 32566287, 2020). "Anemia due to reduced renal production of erythropoietin, as well as iron deficiency and anemia of chronic disease is very common in patients with CKD and ESRD." (PMID 33842491, 2020). "Although rHuEPO has been widely used in tumor-associated anemia, the expression of EPO-R in tumor cells, the working mechanism of EPO and EPO-R, and the results of clinical trials associated with rHuEPO remain controversial." (PMID 32922549, 2020).